ACAT1 (acetyl-CoA acetyltransferase 1)
Diseases named in the same sentence as ACAT1 in open-access papers (continued):
Sharing a sentence is not in itself a finding about the gene and the disease.
prostate carcinoma (continued). "Emerging evidence suggests that a decrease of CE levels via ACAT-1 inhibition significantly improves chemotherapy in melanoma and in prostate cancer cell growth." (PMID 36481936, 2022). "The data from the database and ACAT1 expression in prostate cancer were correlated with the Gleason score." (PMID 36517760, 2022). "In prostate cancer, ACAT1 promotes the expression of P62 and Nrf2 through FUS and affects reactive oxygen species scavenging." (PMID 36517760, 2022). "With increased ACAT1 expression, the proliferation and migration of prostate cancer cell lines enhanced." (PMID 36517760, 2022). "We sought to clarify the role of ACAT1 in prostate cancer by regulating ACAT1 expression in LNCaP and PC3 cell lines." (PMID 36517760, 2022). "That is, ACAT1 promotes prostate cancer by inhibiting autophagy and eliminating active oxygen species." (PMID 36517760, 2022). "Overall, these results demonstrate that SIRT5 regulates the MAPK signalling pathway through ACAT1 and has a tumour‐promoting role in prostate cancer." (PMID 33103371, 2020). "ACAT-1 mediated accumulation of CE was shown to positively correlate with poor survival in pancreatic and prostate cancers." (PMID 31978092, 2020). "Suppression of CE accumulation via ACAT-1 inhibition appeared to significantly impair the tumor growth as observed in pancreatic cancer, prostate cancer and in glioma tissues." (PMID 31978092, 2020). "Abnormal accumulation of acyl-CoA cholesterol acyltransferase-1 (ACAT-1) mediated cholesterol ester has been shown to contribute to cancer progression in various cancers including leukemia, glioma, breast, pancreatic and prostate cancers." (PMID 31978092, 2020). "Compared with benign prostate tissues, ACAT1 expression was significantly increased in prostate cancer tissues." (PMID 31649873, 2019). "In addition, SIRT5 enhances the MAPK signaling pathway through acetyl-CoA acetyltransferase 1 (ACAT1), increasing the ability of prostate cancer cells to proliferate, migrate, and invade." (PMID 39979670, 2025). "In prostate cancer, ACAT1 is upregulated in high-grade cases." (PMID 38817856, 2024). "Notably, in colon and prostate cancer, this treatment translated into a decrease in the tumour burden and increased survival, emphasising the broad applicability of ACAT1 inhibition across different cancer types." (PMID 38610991, 2024). "Additionally, reports indicate increased ACAT1 levels in prostate cancer tissues of patients exposed to organic substances such as dioxins and polychlorinated biphenyls, potentially promoting cancer cell growth and metastasis." (PMID 38817856, 2024). "In addition, it has also been noted in the literature that ACAT1 is highly expressed in lung cancer and prostate cancer." (PMID 36902617, 2023). "Through the GEPIA database, we found that ACAT1 is an oncogene in prostate cancer." (PMID 36517760, 2022). "To elucidate the prostate cancer-promoting role of ACAT1, we screened the STRING database." (PMID 36517760, 2022). "It was also reported that the expression of ACAT1 could serve as a potential prognostic marker in prostate cancer." (PMID 33463049, 2021). "In addition, the esterification of cholesterol for storage in LDs, by sterol O-acyltransferase 1 (ACAT1), has been shown to augment the survival in prostate cancer." (PMID 33194695, 2020). "In addition to our current results in gastric cancer, previous studies have also shown that ACAT1 expression levels in prostate cancer are higher compared to adjacent normal tissues, with ACAT1 and SIRT5 synergistically promoting the development of invasive prostate cancer." (PMID 39247186, 2024). "To further elucidate the role of cholesteryl ester homeostasis in prostate cancer cell proliferation, we next determined whether pharmacological inhibition of ACAT1-catalyzed cholesteryl ester synthesis could block the ability of LDL to stimulate cell proliferation." (PMID 35033184, 2022).
prostate carcinoma (continued). "Moreover, high ACAT1 expression was related to the poor prognosis of patients with prostate cancer." (PMID 36517760, 2022). "Also it has been proposed that ACAT1 expression could serve as a potential prognostic marker in prostate cancer, specifically in differentiating indolent and aggressive forms of cancer." (PMID 33194695, 2020). "We determined that ACAT1 can regulate the MAPK signalling pathway; therefore, we believe that SIRT5 regulates the MAPK signalling pathway through ACAT1, thereby promoting prostate cancer." (PMID 33103371, 2020). "Our results indicate that DGAT1, ABHD5, ACAT1 and ATGL are overexpressed in prostate cancer cells compared to PBMCs and of these overexpressed genes, DGAT1 and ABHD5 aid in the growth of the prostate cancer cells." (PMID 28877685, 2017). "Additionally, in prostate cancer, CAR-T cells were empowered by downregulating the cholesterol esterification enzyme ACAT1 which was also achieved through shRNA technology." (PMID 38835760, 2024). "In these clinical samples, we found that ACAT1 expression was higher in prostate cancer tissues than in normal prostate tissues, and this was in line with the data obtained from the GEPIA." (PMID 36517760, 2022). "Since ACAT1 negatively regulates the MAPK signaling pathway, Peck and Shulze concluded that SIRT5 promotes the proliferation, invasion, and migration of prostate cancer via the downregulation of ACAT1 protein levels." (PMID 36291902, 2022). "Through western blotting, we found that there was negative correlation between the expression of ACAT1 and that of FUS in four common prostate cancer cell lines (LNCaP, PC3, DU145, and 22RV1) (R = -0.9148)." (PMID 36517760, 2022). "Consistent with this concept, pharmacologically targeting cholesteryl ester synthesis by blocking acyl-Coenzyme A: cholesterol acyltransferase 1 (ACAT1) activity impaired androgen-independent, androgen receptor (AR)-negative PC3 prostate cancer cell growth." (PMID 35033184, 2022). "Through laser confocal microscopy, we observed that FUS could co-localize with ACAT1 in the cytoplasm in prostate cancer cells, and FUS not bound to ACAT1 existed in the nucleus of some prostate cancer cells." (PMID 36517760, 2022).
melanoma (20 papers, 2017 to 2025). A malignant, usually aggressive tumor composed of atypical, neoplastic melanocytes. "Increased intracellular cholesterol levels of tumor-infiltrating lymphocytes (TILs) in melanoma are caused by pharmacologically or genetically inhibiting ACAT1, which enhances immunological responses." (PMID 38292487, 2023). "In preclinical melanoma and lung cancer models, deletion of ACAT1 in CD8+ T cells significantly suppressed tumor progression and metastasis." (PMID 40607438, 2025). "Avasimibe, an inhibitor of acetyl-CoA acetyltransferase 1 (ACAT1), has demonstrated significant anti-tumor effects in a mouse model of melanoma." (PMID 39609317, 2024). "The adoptive transfer of mouse CD8+ T cells with a faulty form of ACAT-1 results in a better prognosis for melanoma tumors than wild-type CD8+ T cells." (PMID 38292487, 2023). "Compared with wild-type CD8+ T cells, the adoptive transfer of murine CD8+ T cells with defective ACAT-1 shows improved prognosis of melanoma tumors." (PMID 35062950, 2022). "Inhibiting ACAT1 pharmacologically or genetically increases intracellular cholesterol level in tumor-infiltrating T lymphocytes (TILs) in melanoma, inducing superior immune responses." (PMID 35062950, 2022). "Experimental evidence in cancer immunotherapy shows that inhibition of acetyl-CoA acetyltransferase-1 (ACAT1), an enzyme that increases intracellular esterified cholesterol levels, improves the efficacy of anti–PD-1 therapy in melanoma." (PMID 35040437, 2022). "ACAT1-deficient CD8+ T cells are superior to wild type CD8+ T cells in controlling the growth and metastasis of mouse with melanoma." (PMID 33344447, 2020). "It has been shown that intragastric administration of the ACAT1 inhibitor avasimibe reduces melanoma and lung cancer tumor xenografts in mice, and mice treated with avasimibe survive longer than control mice after melanoma or lung cancer cell injection." (PMID 29295482, 2017). "Besides, in another immunologically cold tumor model, Acat1 suppressed melanoma tumor growth, revalidating its antitumor function." (PMID 40289129, 2025). "In contrast, another study demonstrated that ACAT1 exerts its antitumor effect on melanoma by increasing the abundance of cytokine-producing T cells in tumors;48 whereas, the mechanism by which ACAT1 activates antitumor immunity remains unknown." (PMID 40289129, 2025). "In addition, ACAT1-deficient CD8+ T cells showed better control over the growth and metastasis of melanoma tumours." (PMID 37261073, 2023). "ACAT1 inhibitor (Avasimibe) showed a good anti-tumor effect in melanoma bearing mice." (PMID 33344447, 2020). "Additionally, with regard to immune regulation, Boliang Li’s team has confirmed that acyl-coenzyme A cholesterol acyltransferase 1 (ACAT1)-deficient CD8 + T cells are superior to wild-type CD8+ T cells in controlling the growth and metastasis of melanoma in mice." (PMID 35924044, 2022). "Additionally, attaching liposomes loaded with the ACAT1 inhibitor Avasimibe onto T cell surfaces increases membrane cholesterol content, facilitates rapid T cell receptor clustering, and sustains T cell activation, enhancing their cytotoxic effects against glioblastoma and melanoma." (PMID 40607438, 2025). "Inhibiting ACAT1 in CD8+ T cells led to the increment of PM-cholesterol and subsequently enhanced T-cell cytotoxicity towards melanoma tumors." (PMID 39481851, 2024). "ACAT1 is the major enzyme that catalyzes the synthesis of cholesteryl esters in CD8+ T cells, and pharmacological or genetic inhibition of ACAT1 increases intracellular cholesterol levels in melanoma tumor-infiltrating T lymphocytes (TIL), thereby inducing a superior immune response." (PMID 36046791, 2022).
breast carcinoma (18 papers, 2015 to 2026). "The overexpression of ACAT1 is associated with neoplastic progression and poor prognosis in human high‐grade prostate, pancreatic and breast cancers." (PMID 38213102, 2024). "Notably, all the FA metabolic genes ELOVL6, ACSL1, ACSL3, ACSL4, ACDSB and ACAT1 showed significant positive correlation with NAT10 suggesting that overexpression of NAT10 in breast cancer patients is associated with FA metabolism." (PMID 36149760, 2022). "A correlation between ACAT1 overexpression and poor prognosis was confirmed in high-grade human prostate, pancreatic and breast cancers." (PMID 35399074, 2022). "Abnormal ACAT1 expression and CE levels were found in cancer cells, including those of leukemia, glioma, prostate cancer, pancreatic cancer, breast cancer and colon cancer." (PMID 35399074, 2022). "Bitter melon extract, a natural ACAT-1 inhibitor, exerts antitumor effects towards breast cancer cells." (PMID 34109128, 2021). "It has also been demonstrated that ACAT-1 is a metabolic “tumor promoter”, since it is overexpressed in human breast cancer cells leading to tumor formation and lung metastasis." (PMID 34109128, 2021). "In prostate and breast cancers ACAT1 expression was reported to be significantly greater compared to adjacent benign tissues." (PMID 31921677, 2019). "On the other hand, data show that over expression of ACAT1/2 in human breast cancer cells using a lentiviral approach directly promotes tumor growth and lung metastasis." (PMID 29793481, 2018). "For example, recombinant transduction of human breast cancer cells (MDA-MB-231) with either OXCT1 or ACAT1 is indeed sufficient to metabolically promote tumor growth and metastasis, in pre-clinical models." (PMID 29108233, 2017). "First, considering the reported interactions between SIRT7, FKBP51, and AKT in breast cancer 42, we hypothesize that ACAT1 may regulate the activity of AKT by acetylating a certain kinase and regulating its ability to phosphorylate AKT." (PMID 38817856, 2024). "The upregulation of ACAT1 in breast cancer was shown to induce apoptosis." (PMID 34485115, 2021). "ACAT-1 is overexpressed in two ER- lines of human breast cancer, MDA-MB-231, and MDA-MB-436." (PMID 34109128, 2021). "In further support of this “metabolic-coupling” hypothesis, recombinant over-expression of ACAT1 or OXCT1 in MDA-MB-231 breast cancer cells was indeed sufficient to promote tumor growth and lung metastasis." (PMID 29108233, 2017). "Importantly, over-expression of OXCT1 or ACAT1 in human breast cancer cells is sufficient to genetically drive tumorigenesis and/or lung metastasis, validating that they indeed behave as metabolic “tumor promoters”." (PMID 29108233, 2017). "Nuclear receptor subfamily 2 group F member 6 (NR2F6) could transcriptionally activate ACAT1 and enhance the suppressive role of ACAT1-induced METTL3 acetylation on cell migration and invasion of breast cancer." (PMID 38720812, 2024). "In breast cancer, the top-ranked gene was ACAT1 (Acetyl-CoA acetyltransferase, not be confused with the enzyme acyl-Coenzyme A: cholesterol acyltransferase 1, which is encoded by the gene SOAT1)." (PMID 25961905, 2015). "Although eQTL analysis has identified cis-eQTL associations between several variants and ACAT1, ATM as well as other neighboring genes in both breast carcinoma and normal breast tissues, none of these associations involved the most significantly associated risk SNPs." (PMID 27796716, 2017).
pancreatic cancer (14 papers, 2016 to 2024). "If the presence of high sterol ester subtype of NSCLC can be confirmed, ACAT1 becomes a promising therapeutic target given that inhibition of ACAT1 has been shown to cause apoptosis in pancreatic cancer via a buildup of intracellular cholesterol and increased endoplasmic reticulum stress." (PMID 34822397, 2021). "Accumulation of cholesteryl esters (CEs) is another characteristic of cancer; for example, Acetyl-CoA acetyltransferase 1 (ACAT1) is correlated with pancreatic cancer and lymphocytic leukemia." (PMID 38921447, 2024). "Abrogation of cholesteryl ester accumulation via enzymatic inhibition or depletion of ACAT1 was identified as a potent therapeutic strategy to intercept cancer progression and tumor metastasis in orthotropic mouse model of pancreatic cancer." (PMID 39243069, 2024). "In a mouse mesothelin-expressing pancreatic carcinoma model, the inhibition of cholesterol acyltransferase 1 (ACAT-1) in CAR-T cells resulted in significant tumor regression." (PMID 38890370, 2024). "Consistently, ACAT1 overexpression was confirmed in many cancers, including hepatocellular carcinoma, castration-resistant prostate cancer, and pancreatic cancer." (PMID 37089950, 2023). "In contrast to the positive role of cholesterol in pancreatic cancer progression, high-level free cholesterol with ACAT-1 inhibition results in severe endoplasmic reticulum (ER) stress and cancer cell apoptosis." (PMID 32122374, 2020). "After that, excessive free cholesterol is stored as cholesteryl ester within pancreatic cancer cells after esterification, which is mediated by highly expressed acyl-CoA cholesterol acyl-transferase-1 (ACAT-1)." (PMID 32122374, 2020). "Aberrant accumulation of cholesteryl ester is also observed in pancreatic cancer patients, and ACAT1 expression is correlated with poor patient survival." (PMID 29295482, 2017). "These evidences collectively support ACAT-1 is the major isoform that promotes the CE accumulation in pancreatic cancers." (PMID 27132508, 2016). "Taken together, ACAT-1 inhibition induced an increase of intracellular free cholesterol, ER stress and apoptosis in pancreatic cancer cells." (PMID 27132508, 2016). "Abrogation of cholesterol esterification, either by an ACAT-1 inhibitor or by shRNA knockdown, significantly suppressed tumor growth and metastasis in an orthotopic mouse model of pancreatic cancer." (PMID 27132508, 2016). "Collectively, these data demonstrate the therapeutic potential of ACAT-1 inhibition for pancreatic cancer treatment." (PMID 27132508, 2016). "These clinical data suggest that ACAT-1 expression is a potential prognosis marker for pancreatic cancer." (PMID 27132508, 2016). "The overexpression of ACAT-1 in cancer tissues suggests a potential role of ACAT-1 in pancreatic cancer progression." (PMID 27132508, 2016). "By using label-free Raman spectromicroscopy, we found an aberrant accumulation of cholesteryl ester in human pancreatic cancer specimens and cell lines, mediated by acyl-CoA cholesterol acyltransferase-1 (ACAT-1) enzyme." (PMID 27132508, 2016). "Abrogation of cholesterol esterification, either by inhibiting ACAT-1 enzyme activity or by shRNA knockdown of ACAT-1 expression, significantly reduced pancreatic tumor growth and metastasis in an orthotopic mouse model." (PMID 27132508, 2016). "ACAT-1 was overexpressed in MIA PaCa-2 human pancreatic cancer cells compared to normal cells, and treatment of cells with avasimibe or knockdown of the ACAT-1 gene results in a block of cholesterol esterification, and a decrease in cell invasion and migration." (PMID 37089950, 2023). "In addition, once in the ER, LDL-derived cholesterol can be esterified by ACAT1 for storage as cholesteryl ester in lipid droplets, serving as an important source of cholesterol in cancer cell growth, as shown for prostate and pancreatic cancers." (PMID 35806209, 2022). "Upregulation of ACAT1 was correlated with more aggressive pancreatic cancer." (PMID 31649873, 2019).
pancreatic cancer (continued). "As expected, ACAT-1 shRNA effectively suppressed CE accumulation in pancreatic cancer cells." (PMID 27132508, 2016). "Interestingly, in pancreatic cancer poor patient prognosis was connected to ACAT1 expression." (PMID 39243069, 2024). "Inhibition of ACAT1 or knockdown with shRNA activates ER stress response/ unfolded protein response (UPR) signaling and reduces pancreatic cancer cell proliferation as well as tumor development in mice." (PMID 29295482, 2017). "Together, our results indicate that CE accumulation in pancreatic cancer arises from both de novo synthesis and LDL uptake, and is mediated by the ACAT-1 enzyme." (PMID 27132508, 2016). "By using avasimibe, a potent inhibitor of ACAT-1, we found that pancreatic cancer cells MIA PaCa-2 and PANC-1 were much more sensitive to ACAT-1 inhibition than normal HPDE6 cells." (PMID 27132508, 2016). "To correlate ACAT-1 expression with patient outcome, we performed immunohistochemistry of ACAT-1 in a pancreatic cancer tissue array." (PMID 27132508, 2016).